CES1 (carboxylesterase 1)
Diseases named in the same sentence as CES1 in open-access papers (continued):
Sharing a sentence is not in itself a finding about the gene and the disease.
tumor (32 papers, 2014 to 2026). "CES1 emerged as a robust predictor of poor survival and immunotherapy resistance, closely associated with tumor progression, extracellular matrix remodeling, and an immunosuppressive, fibroblast-rich TME." (PMID 41882633, 2026). "Knockdown and overexpression models of CES1 were created in SCC-9 and patient-derived organoid (PDO) cells using shRNA and lentivirus to investigate the tumor biology and cisplatin resistance associated with CES1." (PMID 39574476, 2024). "To further test the synergistic effect of loss of function of CES1 and treatment of cisplatin, we performed a tumor growth assay in HepG2 xenografted NU/J mice." (PMID 36472914, 2023). "Carboxylesterase1 (CES1), an enzyme involved in lipids hydrolysis, lipoproteins assembly and fatty acyl and cholesterol ester metabolism, also implicated in tumour-killing activity of monocytes showed significant lower level in syndromic fibroblasts." (PMID 34831015, 2021). "The MAGL inhibitor JZL184 also efficiently inhibited CES1 in vitro and in vivo, increasing glycerol esters and reducing tumor progression." (PMID 39934865, 2025). "Tumor measurements showed that sh-CES1 significantly reduced both tumor volume and weight compared to sh-NC, whereas OE-CES1 promoted tumor growth relative to the OE-NC group." (PMID 40771823, 2025). "Previous studies have shown that pharmacological or genetic inhibition of CES1 alters lipid metabolism, compromises mitochondrial function, and sensitizes tumor cells to chemotherapeutic agents." (PMID 40650205, 2025). "Immunohistochemical analysis of Ki67 in tumor tissues showed significantly lower expression in the sh-CES1 group, while the OE-CES1 group exhibited higher expression." (PMID 40771823, 2025). "CES1 protein decreases as the tumor shrinks following the intervention (p < 0.01) and increases with tumor growth after re-exposure to smoke intervention (p < 0.05)." (PMID 39472448, 2024). "We further investigated the expression related to laryngocarcinoma tissue microarrays and found that as CES1 increases in laryngocarcinoma, the expression of the tumor proliferation and metastasis-related protein Ki-67 also rises (p < 0.05)." (PMID 39472448, 2024). "Subsequently, we performed in vitro studies by HNSCC-PDO and SCC-9 and found that CES1-overexpressing cells exhibited reduced sensitivity to cisplatin and stronger tumor malignant biological behavior compared with CES1-knockdown cells." (PMID 39574476, 2024). "By enhancing fatty acid oxidation and preventing triglyceride toxicity, CES1 can promote tumor initiation, progression, and metastasis, and elevated CES1 expression is associated with poor prognosis." (PMID 39472448, 2024). "We also found that the total expression of CES1 gradually increased as tumor invaded deeper although its expression is higher in normal tissues." (PMID 36816947, 2023). "Consistently, we detected a decreased ratio of phosphorylated AKT and total AKT in CES1-KO xenografts, suggesting reduced tumor growth." (PMID 36472914, 2023). "In the model, FFAs produced by CES1 fuel the mitochondria for β-oxidation and ATP production to support tumor growth." (PMID 36472914, 2023). "Overall, these results indicate that MLT inhibits tumor growth by upregulating the CES1 expression in vivo." (PMID 34185414, 2021). "The expression of CES1 was downregulated in PCa tissues compared to normal prostate tissues, and the high expression of CES1 is negatively correlated with tumor stage, metastasis, and Gleason score." (PMID 34185414, 2021). "CES1 expression could potentially serve as a biomarker in any tumor type that is sensitive to DRP-104." (PMID 38536921, 2024). "NF-κB-driven CES1 expression has been observed to be related to tumor cachexia and inflammation." (PMID 39472448, 2024).
tumor (continued). "Indeed, this tumor expressed six of the NRF2 targets (CES1, CYP4F1, GSTM3, ARK1C1/3/4, AKR1C2, SRXN1, and PTGR1) more than 16-fold above their respective mean expressions for the entire cohort and 24 proteins more than 4-fold above their means." (PMID 37716475, 2023). "However, when we combined the approaches of CES1 blockage and administration of the anticancer agent cisplatin, we detected a synergistic effect of cell apoptosis and tumor inhibition in HCC." (PMID 36472914, 2023). "In conclusion, blocking CES1 activity impairs the respiratory function of mitochondria, which may affect the progression of tumor growth." (PMID 36472914, 2023). "Consequently, the enhanced mitochondrial function and increased levels of SCD induced by CES1 activation promote tumor growth and potential chemoresistance (left)." (PMID 36472914, 2023). "Notably, this tumor subtype-based distribution and unfavorable prognostic correlation distinguished CES1 from all other human intracellular TAG lipases, suggesting that CES1 plays a unique role in the etiopathogenesis of CRC." (PMID 35252551, 2022). "Compared with endocrine therapy that eventually fails and leads to lipid accumulation, MLT treatment or restoration of CES1 expression is to repress lipid/cholesterol accumulation, promote tumor cell slimming in tumors and reduce de novo intratumoral androgen synthesis." (PMID 34185414, 2021). "Notably, BODIPY staining revealed sparse lipid deposition in the MLT‐treated tumor compared to that in the control tumor; knockout of CES1 expression increased lipid accumulation and reversed the effect of melatonin." (PMID 34185414, 2021). "Knockout of CES1 reversed the effect of MLT on tumor growth." (PMID 34185414, 2021). "Transwell and CCK‐8 assays were executed to examine whether CES1 is involved in the regulation of tumor growth and metastasis of PCa cells." (PMID 34185414, 2021). "Interestingly, the inhibition of CES1 in monocytes was shown to diminish their ability to lyse tumor cells." (PMID 32466188, 2020). "Therefore, CES1 plays a significant role in tumor proliferation and metastasis." (PMID 39472448, 2024). "In HNC, CHRNA5 was found to mediate nicotine‐induced proliferation, migration, and invasion by regulating CES1 via the MEK/ERK pathway, contributing to tumor recurrence and metastasis." (PMID 41201200, 2025). "Annotation of F3 as iCAF was further consistent with our recent study demonstrating expression of CES1 and PAGE4 by C1 prostate fibroblasts exhibiting an iCAF-like phenotype and in PIN and low Gleason tumours." (PMID 41378308, 2025). "Carboxylesterases CES1 and CES2 in the normal range should correspond to zero resistance of the tumour cells to camptothecin compounds, topoisomerase I inhibitors." (PMID 40347057, 2025). "To test this, we conducted a series of experiments and observed that CES1 promotes AML progression and macrophage M2 polarization in both AML cells and AML xenograft tumor models." (PMID 40771823, 2025). "Adipose-derived stem cells overexpress TRAIL and CES1, and CPT-11 significantly inhibits tumor growth and enhances apoptosis." (PMID 40839370, 2025). "Therefore, we hypothesized that CES1 may be a tumor suppressor gene in PCa." (PMID 34185414, 2021). "Moreover, CES1 influenced the proportion of nine types of tumor-infiltrating immune cells (TICs), particularly M2 macrophages, as supported by functional studies involving CES1 knockdown and overexpression in AML cells and AML xenograft tumor models." (PMID 40771823, 2025). "To further validate the effect of CES1 in vitro, we subcutaneously injected HL-60 cells treated with sh-NC, sh-CES1, OE-NC, and OE-CES1 into mice to evaluate the role of CES1 in AML xenograft tumor growth." (PMID 40771823, 2025).
tumor (continued). "Since the enhancement of TurboID biotinylation efficiency by BME in living cells depends on the expression of CES1 and CES2, we compared the expression of these genes in the common tumor cell lines (HeLa, HEK293T, and U937) and in normal endothelial, fibroblast, epithelial, and epidermal cells." (PMID 41402538, 2025). "Tumor western blot experiments and qRT-PCR validation confirmed that p-MEK/MEK, p-ERK/ERK, and CES1 levels decreased with the knockdown of CHRNA5, whereas nicotine reversed this trend in the SH group, indicating that CHRNA5 regulates CES1 expression through the MEK/ERK pathway." (PMID 39472448, 2024). "A similar inhibitory effect on xenograft growth was observed in CES1-KO HepG2 cells when treated with cisplatin (10 μmol/kg), while ablation of CES1 itself did not affect the CES1-KO xenograft tumor growth." (PMID 36472914, 2023). "While future studies will determine whether CES1 blockade can be developed into an effective treatment in obese CRC patients, our findings may serve as an example for developing tumor subtype-based interventions also in cancers beyond CRC." (PMID 35252551, 2022). "Moreover, LAN‐mediated circadian rhythm disorder downregulated the expression of Ces1 and Sirt1, upregulated the expression of Dnmt1, while MLT supplementation eliminated the effects in the mouse tumor tissues." (PMID 34185414, 2021). "Unexpectedly, even though blocking CES1 activity impairs mitochondrial function and reduces SCD levels, both of which might vitally affect the growth and proliferation of tumor cells, we only observed a mild effect of cell apoptosis in WWL229-treated and CES1-KO HepG2 cells." (PMID 36472914, 2023). "Future studies using single-cell (sc)RNA sequencing and patient-derived organoid (PDO) 3D co-cultures may help to clarify these potential added roles of CES1 in non-cancerous cells of the tumor microenvironment." (PMID 35252551, 2022). "There were also genes that are of insignificant expression in tumor cells that increase in expression in KO cells, e.g. THBS3, IL2RG, SPRR3, TGM2, HMOX1 and TMEM62 or are lower in expression in tumor cells and significantly decreased in KO cells such as MAN1A1, CES1, STCBP6, SIVA1 and TMEM40." (PMID 31797958, 2019). "Moreover, tumor cells present up-regulated expression of carboxylesterase 1 when compared with non-neoplastic cells." (PMID 25850034, 2015). "Whilst the abundance of PAGE4+ or CES1+ cells did not significantly differ between these two tumor types, PAGE4+/CES1+ cells tended to accumulate in nests within intraglandular areas of stromogenic tumors." (PMID 41327318, 2025). "It is also not clear to what extent CES1 is excreted and able to enzymatically activate DRP-104 in the extracellular space of the tumor microenvironment, where it can directly affect T cell function." (PMID 38536921, 2024). "The total expression of CES1 was significantly lower in advanced CRC tissues than in normal tissues, but its expression gradually increased as tumor invaded deeper." (PMID 36816947, 2023).
cancer (20 papers, 2017 to 2026). A tumor composed of atypical neoplastic, often pleomorphic cells that invade other tissues. "Interestingly, some studies have implicated CES1 expression in cancer pathophysiology as a biomarker and a potential therapeutic target for hepatocellular carcinoma and colorectal cancer." (PMID 39934865, 2025). "Despite limited research on the role of CES1 in malignant tumors, this study utilizes bioinformatics and cell molecular biology experiments to investigate the significance of CES1 in HNSCC, and its potential as a prognostic marker." (PMID 39574476, 2024). "We further analyzed CES1 expression in other cancer types based on the available databases (tnmplot.com, xena.ucsc.edu, and kmplot.com)." (PMID 36472914, 2023). "We then analyzed the correlation between the protein levels of CES1 and survival probability in different cancers." (PMID 36472914, 2023). "Based on these computational findings and the biological relevance of CES1 in cancer, we propose that CES1 may represent a promising molecular target for RA and its derivatives." (PMID 40650205, 2025). "Importantly, treatment with the SCD-specific inhibitor MF438 efficiently blocked the CES1 effect on HCC apoptosis, further highlighting the key role of SCD in CES1-mediated cancer cell growth." (PMID 36472914, 2023). "Additionally, we observed significant expression of CLDN6, CES1, SOST, SPRR2A, MYBPH, CGB5, and KRT1 in the high-risk group, suggesting their potential involvement as cancer-promoting genes in BLCA development." (PMID 37780567, 2023). "Besides, we used the Cancer Cell Line Encyclopedia database to evaluate the methylation status of the CES1 promoter in several PCa cell lines and found that the methylated CES1 promoter is relatively enriched in CRPC cells." (PMID 34185414, 2021). "CES1 is the major hydrolytic enzyme responsible for the biotransformation of many and diverse therapeutic agents including Angiotensin-converting-enzyme inhibitors, anti-cancer prodrugs, narcotic drugs, methylphenidate, and others." (PMID 31362390, 2019). "In summary, our experimental and metaanalysis results suggest that CES1 is expressed at various levels in HCC and many other cancer types." (PMID 36472914, 2023). "Indeed, as CES1 is also expressed in adipocytes, targeting lipolysis with CES1 inhibitors may cut off the FFA supply to cancer cells from both endogenous LDs and CAAs." (PMID 35252551, 2022). "The impact of CES1 on the sensitivity of HNSCC to cisplatin remains not completely understood, with a complex mechanism involving changes in cancer stem cell phenotype, epithelial-mesenchymal transition, drug efflux, autophagy, and metabolic reprogramming." (PMID 39574476, 2024).
infection (8 papers, 2017 to 2025). The state of being infected such as from the introduction of a foreign agent such as serum, vaccine, antigenic substance or organism. "Transcript levels of some of the key DMEs were upregulated in the liver of the infected mice, 8 weeks post-infection like Nat2, Cyp2e1, Slco1b2, Ces1, Ces2, and Aadac (upregulated by almost 2–3-fold)." (PMID 41358489, 2025). "Three weeks after Ad-shCes1 infection, hepatic Ces1/Ces1g mRNA and protein levels were reduced by ~90% whereas intestinal CES1g protein levels were unchanged." (PMID 29259301, 2017). "Subsequent functional validation involved creating CES1-knockdown and overexpression models in SCC-9 and HNSCC PDO through shRNA transfection and lentiviral infection." (PMID 39574476, 2024).
metabolic disease (6 papers, 2016 to 2024). A congenital disorder (due to inherited enzyme abnormality) or acquired (due to failure of a metabolically important organ) disorder resulting from an abnormal metabolic process. "Taken together with our findings of the regulation of CES1 by Nrf2, it can be concluded that one mechanism by which Nrf2 activation protects against metabolic disorders is through induction of CES1." (PMID 33103077, 2020). "Furthermore, the role of this enzyme in lipid metabolism suggests that CES1 is a potential drug target for the treatment of metabolic diseases." (PMID 36553492, 2022).
cardiovascular disease (3 papers, 2021 to 2025). "We found 6 proteins that mediated the PGSCAD’s effect on MACE in EXSCEL (C9, LBP, ITIH4, APOM, CES1, and HS6ST2), providing supporting evidence that they might serve as biomarkers for cardiovascular disease in patients with T2D52–54." (PMID 40032831, 2025).
inflammation (1 paper, 2016). Aberrant reaction of the microcirculation characterized by movement of fluid and leukocytes from the blood into extravascular tissues. "CES1 deficiency causes elevated levels of acetaldehyde, H2O2, MDA and FFAs as well as mitochondrial dysfunctions, which are known to contribute to liver inflammation and liver damage." (PMID 27075303, 2016).
liver (1 paper, 2016). "Targeting hepatic CES1 may represent a novel strategy for prevention and treatment of ALD and non-alcoholic liver injury." (PMID 27075303, 2016).
movement disorder (1 paper, 2024). Neurological conditions resulting in abnormal voluntary or involuntary movement, which may impact the speed, fluency, quality and ease of movement. "However, the CES1 gene deletion does not explain the movement disorder observed in the family." (PMID 39180521, 2024).
CES1 also shares sentences with these, for which no sentence is quoted: aneurysm (2 papers); colon carcinoma (2); epilepsy (2); Hyperinsulinemia (2); liver disease (2); schizophrenia (2); Stroke (2); acute myocardial infarction (1); adenocarcinoma (1); adenoma (1); adrenocortical carcinoma (1); alcohol (1); Alzheimer disease (1); autoimmune hemolytic anemia (1); autoimmune pancreatitis (1); B-cell chronic lymphocytic leukemia (1); cardioembolic stroke (1); cholangiocarcinoma (1); depression (1); dyslipidaemia (1); E. coli infections (1); endometrial cancer (1); gastric adenocarcinoma (1); glaucoma (1); haemorrhages (1); hepatitis (1); hepatoblastoma (1); Hyperglycemia (1); Hypocholesterolemia (1); Impaired glucose tolerance (1).
A further 16 diseases each share a sentence with CES1 in 1 paper.